XCL2 (X-C motif chemokine ligand 2)
Description:
Chemotactic activity for lymphocytes but not for monocytes or neutrophils.
Synonyms: SCYC2; SCM-1b; SCM1B
Tractability: Antibody: its Gene Ontology location is reachable by antibodies, with high confidence; UniProt places it where antibodies can reach, with medium confidence; UniProt predicts a signal peptide or a membrane-spanning region.
Gene: Protein-coding gene on chromosome 1 (168,540,768 to 168,543,997, reverse strand). Ensembl gene ENSG00000143185.
Subcellular location: Secreted
Pathways (Reactome):
Signal Transduction: Chemokine receptors bind chemokines; G alpha (q) signalling events
Gene Ontology:
Molecular function: protein binding; CCR chemokine receptor binding; chemokine activity
Biological process: antimicrobial humoral immune response mediated by antimicrobial peptide; blood circulation; cell chemotaxis; chemokine-mediated signaling pathway; inflammatory response; positive regulation of cell migration; signal transduction; immune response
Cellular component: extracellular region
Genetic constraint (gnomAD): Loss-of-function variants: 5 observed, 6 expected, observed/expected ratio (o/e) 0.83, 90% interval 0.43 to 1.66. That is too few expected variants to judge how well the gene tolerates losing a copy. Missense variants: 127 observed, 126.02 expected, observed/expected ratio (o/e) 1.01, 90% interval 0.87 to 1.17. Synonymous variants: 46 observed, 49.14 expected, observed/expected ratio (o/e) 0.94, 90% interval 0.74 to 1.2.
Homologues: Orthologues: chimpanzee XCL2 (97% identical), macaque XCL1 (89% identical), pig XCL1 (67% identical), mouse Xcl1 (61% identical), rat Xcl1 (55% identical), zebrafish cxcl32b.1 (28% identical). Paralogues in human: XCL1 (98% identical), CCL8 (29% identical), CCL7 (27% identical), CCL26 (25% identical), CCL4 (25% identical), CX3CL1 (25% identical), CCL11 (25% identical), CCL2 (25% identical), CCL13 (24% identical), CCL23 (24% identical), CCL3L3 (24% identical), CCL15 (23% identical), and 14 more.
Diseases named in the same sentence as XCL2 in open-access papers:
XCL2 is named in the same sentence as 26 diseases in open-access papers, as found by Europe PMC text mining. Sharing a sentence is not in itself a finding about the gene and the disease. The quoted sentences say what the papers report.
breast carcinoma (4 papers, 2007 to 2025). "XCL2 encodes for a protein that enhances chemotactic activity for lymphocytes and downregulation of XCL2 has been shown to be associated with good prognosis in patients with breast cancer." (PMID 22134506, 2012). "Böttcher and colleagues analyzed The Cancer Genome Atlas data and found that a cDC1 signature was positively correlated with an XCL1/XCL2 and CCL5 chemokine signature and an NK-cell signature in breast cancer, melanoma, and lung adenocarcinoma." (PMID 39777457, 2025). "There was no significant downregulation of PLP2 and XCL2 in MCF-7 breast cancer cells." (PMID 22134506, 2012). "The specificity of our prognostic module to ER- breast cancer was confirmed by application of PAC, which showed that, with the exception of XCL2, none of the other six genes were individually prognostic." (PMID 17683518, 2007).
COVID-19 (4 papers, 2021 to 2023). A disease caused by infection with severe acute respiratory syndrome coronavirus 2. "CD4 T-cells with cytotoxic activity (CD4 CTLs) and NK-cells displayed enhanced interferon signaling and effector activation markers (GZMB, GZMH, CCL4, XCL2) in patients who succumbed to COVID-19." (PMID 35169146, 2022). "In contrast, CD4 CTL T-cells and NK-cell subsets displayed increased expression of effector activation markers (GZMB, GZMH, CCL4, XCL2) and ISGs in patients who succumbed to COVID-19." (PMID 35169146, 2022). "We observed that the pulmonary environment of mild COVID-19 patients induced the upregulation of only five pro-inflammatory genes in MSCs, which code for the chemokines CCL5 and XCL2, plus TRAF1, which has already been identified as an important inflammatory mediator in the lungs." (PMID 35095855, 2021).
melanoma (4 papers, 2018 to 2025). A malignant, usually aggressive tumor composed of atypical, neoplastic melanocytes. "In this study, two populations of NK cells were identified: NKCyto (which compared with NK cells from OT metastatic melanoma lesions from NRs, expressing GNLY, CXC3R1, and FCGR3A) and NKRest (expressing XCL1 and XCL2)." (PMID 40530504, 2025). "Similar to the analyses of cDC1 and NK cell gene signatures, we observed a positive correlation with survival when we ranked melanoma, HNSC and TNBC patients according to expression of CCL5, XCL1, and XCL2." (PMID 29429633, 2018).
lung carcinoma (3 papers, 2020 to 2025). "Several studies demonstrated that XCL2 expression increases with lung cancer progression." (PMID 37905956, 2023). "XCL2 expression increases with the degree of malignancy of lung cancer, indicating that it could be an important target in gene therapy for lung cancer." (PMID 32341755, 2020).
ovarian carcinoma (2 papers, 2013 to 2014). A malignant neoplasm originating from the surface ovarian epithelium. "Chemokines lymphotactin 1 and lymphotactin 2, XCL1 and XCL2, respectively, bind and activate XCR1, leading to increased proliferation and migration of ovarian cancer cells that express XCR1." (PMID 24384839, 2013). "The ovarian carcinoma cells themselves express XCL1, and XCL2 is detected in the ascites from ovarian carcinoma, suggesting that XCL/XCR1-driven cell proliferation and migration could contribute to growth and expansion of peritoneal metastasis." (PMID 24384839, 2013).
breast tumor (1 paper, 2016). "Several genes associated with myeloid derived suppressor cells (MDSC) activity (including TNFAIP3 and XCL2), were also observed to be upregulated in both the breast tumor and the placenta tissue." (PMID 27852037, 2016).
liver inflammation (1 paper, 2024). "Immature neutrophils circulating in advanced MASH patients also expressed an array of pro-inflammatory chemokines that can aggravate and perpetuate liver inflammation, such as CCL2, CCL3, CCL5, CXCL1, and XCL2." (PMID 38791066, 2024).
migraine (1 paper, 2023). "Furthermore, we integrated the plasma proteomic dataset with migraine GWAS data for another PWAS, identifying five more genes (MRVI1, PAPPA, B3GNT8, XCL2, and EPHA10) as potential risk genes." (PMID 37592229, 2023).
Pleural effusion (1 paper, 2025). The presence of an excessive amount of fluid in the pleural cavity. "ELISA results confirmed that XCL2 concentration was significantly lower in MPE from LCP than in pleural effusion from HP." (PMID 40959273, 2025).
prostate carcinoma (1 paper, 2021). A carcinoma that arises from epithelial cells of the prostate gland. "These cells showed increased expression of CCL5, XCL1, and XCL2 in prostate cancer, with the potential to recruit cDC1." (PMID 34936871, 2021).
renal carcinoma (1 paper, 2023). A carcinoma arising from the epithelium of the renal parenchyma or the renal pelvis. "It is shown that XCL2 is upregulated in various human cancers and correlated with activated T-cell immune signatures in renal cancer." (PMID 38022530, 2023).
rheumatoid arthritis (1 paper, 2014). A chronic, systemic autoimmune disorder characterized by inflammation in the synovial membranes and articular surfaces. "Xcr1 is the receptor for Xcl1 and Xcl2, which were not part of our microarray, but it is known that Xcrl also plays a role in rheumatoid arthritis and in the recruitment of cells to arthritic joints." (PMID 24967215, 2014).
tumor (38 papers, 2012 to 2026). "We calculated the stromal, immune, and ESTIMATE scores and tumor purity of 33 cancers using Spearman’s correlation analysis and found that immune scores were positively associated with XCL2 expression, especially in BRCA, GBM, KIRC, and THCA." (PMID 37905956, 2023). "Significantly associated with TLS maturity and infiltration, XCL2 is a chemokine produced by NK cells that stimulates DC recruitment into the tumor microenvironment." (PMID 36776859, 2023). "In a previous study, a high expression level of XCL2 was revealed to be associated with NK cells in tumor-immune activities." (PMID 35480120, 2022). "Furthermore, XCL2 affects DNA methylation, tumor mutation burden (TMB), microsatellite instability (MSI), and mismatch repair (MMR) in human cancers." (PMID 37905956, 2023). "Furthermore, we also found that both XCL1 and XCL2 had much more elevated expression in patient tumour samples compared to their matched normal (P < 0.0001), and within tumour samples, high XCL1 expression was significantly associated with worse overall survival." (PMID 39419971, 2024). "However, CNVs are caused by the action of XCL2, which is highly expressed in tumor tissues." (PMID 37905956, 2023). "The main problem for playing the anti-tumor role of XCL1+ CD8+ T cells is the low expression of XCL1 and key related genes (XCR1 and XCL2) in tumor microenvironment of HCC." (PMID 41426973, 2025). "NK cells secrete cytokines and chemokines, such as CCL5, XCL1, and XCL2, which promote dendritic cell migration into solid tumors, and enhance the anti-tumor activity of CD8+ T cells." (PMID 40657373, 2025). "NK cells can also drive tumor inflammation by producing chemokines (XCL1 or XCL2) or cytokines (e.g., IFN-γ) and recruiting and maturing other immune cells to form the tumor microenvironment." (PMID 39668817, 2024). "The results demonstrated that XCL2 acts as a specific oncogene in most tumor types and as an oncogene repressor in tumors and that XCL2 expression is crucial for tumor prognosis." (PMID 37905956, 2023). "This confirmed our earlier suspicion that XCL2 acts as an important chemokine in the recruitment of large numbers of T lymphocytes and macrophages to kill tumor cells." (PMID 37905956, 2023). "XCL2 is a chemokine produced by NK cells that stimulates DC recruitment in the tumor microenvironment." (PMID 36776859, 2023). "Considering the function of the XCL2 gene and its important role for the tumour microenvironment in current cancer therapy, we focused our studies on immune cell infiltration." (PMID 37905956, 2023). "Another tumor-infiltrating XCL1high NK subcluster that expressed a high level of genes associated with the recruitment of DCs (XCL1, XCL2, and FLT3LG) was more highly detected in the PD-1+SMI than in the PD-1 group." (PMID 37430270, 2023). "The survival time of patients was instead reduced, which contradicts the conclusion of our study that patients with high expression of XCL2 should have longer survival due to the anti-tumour effect of M1-type macrophages." (PMID 37905956, 2023). "Tumor-infiltrating NK cells differentiate into two main populations with distinct profiles of chemokine gene expression: XCL1+XCL2+ NK cells and CCL3+CCL4+CCL4L2+CCL5+ NK cells." (PMID 33424862, 2020). "Tumour cell GI was associated with downregulation of PLP2 and XCL2 as well as with disruption of the mitotic spindle." (PMID 22134506, 2012). "This shows that XCL2 could be used as a tumor suppressor to inhibit the growth of tumor cells by recruiting M1 macrophages." (PMID 37905956, 2023). "Therefore, we investigated the relationship between XCL2 expression and the degree of immune cell infiltration to examine the role of XCL2 in tumor immunity." (PMID 37905956, 2023). "In the present study, we found that XCL2 could be used as a target for tumor immunotherapy to enhance its efficacy." (PMID 37905956, 2023). "The trend of XCL2 expression in cell clusters was nearly identical in all tumor samples." (PMID 37905956, 2023).
tumor (continued). "In this study, we comprehensively explored the role of XCL2 in different tumor types by performing panoramic analysis, which is the first of its kind in pan-cancer analysis, using bioinformatics analysis combined with tumor tissue immunofluorescence and macrophage chemotaxis assays." (PMID 37905956, 2023). "Based on previous studies of XCL1 and XCL2, we hypothesized that XCL2 might be involved in the formation and accumulation of immune cells such as T lymphocytes, B lymphocytes, and macrophages during the progression of tumor cells." (PMID 37905956, 2023). "While in detail, exhausted CD8+T and CD4+T cells were increased, and XCL2+NK and FGFBP2+NKT cells were decreased in LN+AM compared to those in LN−AM, indicating a compromised anti-tumor TME." (PMID 38065972, 2023). "Recruitment of cDC1s into the tumor site is also crucial for their anti-tumor activity and depends on the presence of different chemokines in the TME—such as XCL1, XCL2 and CCL5—mainly produced by NK cells." (PMID 37190135, 2023). "Among them, CXCL9 is crucial for recruiting immune T cells into the TME35, XCL2 plays a role in recruitment of DCs36, and CXCL13 can recruit both T cells and B cells into tumor tissues to enhance tumor immunity." (PMID 34556668, 2021). "Although blood and tumor-infiltrating NK cells express predominantly perforin and granzyme genes that are related to cytotoxicity, tumor-infiltrating NK cells upregulate XCL1, XCL2, CCL3, CCL4, CCL4L2, and CCL5 that are chemokine genes." (PMID 33424862, 2020). "In tumor-infiltrate Tregs, we found that IFIT2, CCL3, RBPJ, etc. were upregulated in GC tissues compared to adjacent normal tissues while IGJ, XCL1, XCL2, etc. were downregulated." (PMID 32039830, 2020). "Tumor-associated CD8+ T cells expressing exhaustion markers across all four tumor types project onto activated CD8+ T cells in our map, and express genes within the Cytokine module (CCL3, CCL4, XCL1, XCL2, and IFNG), and to a lesser extent Cytotoxic module." (PMID 31624246, 2019). "Circulating tumor cells can enhance HLA-E expression and bind to CD94 (KLRD1)/NKG2A on NK cells, thereby weakening NK-mediated tumor cell killing and cDC1 recruitment via XCL2 secretion." (PMID 40959273, 2025). "Among them, the chemokine family, including CC (e.g., CCL1, CCL3, CCL5, CCL7, and CCL15), CXC (e.g., CXCL1, CXCL3, CXCL5, and CXCL10), XC (e.g., XCL1 and XCL2), and CX3C (e.g., CX3CL1), plays a pivotal role in tumor development, metastasis, and chemotherapy resistance 30-33." (PMID 40740234, 2025). "The chemokine and receptor profiles of tumor-infiltrating NK1 and NK5 showed increased expression of CCL5, CCL4, XCL1, XCL2, and CXCR3, suggesting that they may be involved in NK tumor homing and activation." (PMID 40315330, 2025). "In addition, we found significant upregulation of the CXCL13, XCL2, and CXCL17 genes in samples with TLS infiltration in the tumor." (PMID 36776859, 2023). "Complementing the hypothesis that cDC1s migrate in the tumor through the XCL1/2 – XCR1 axis, we show that, besides for NK-cells, XCL1/XCL2 were also expressed by a subpopulation of ENTPD1+ ITGAE+ CD8+ T-cells." (PMID 36741389, 2022). "Notably, the C2-CD8 cluster was characterized by low expression of cytokines/chemokines (CCL3, CCL4L2, XCL1, and XCL2), which might hinder infiltration of effector CD8 T/NK cells and DCs into the peritoneum for their anti-tumor functions." (PMID 36788228, 2023).
cancer (12 papers, 2013 to 2025). A tumor composed of atypical neoplastic, often pleomorphic cells that invade other tissues. "The mutation types of XCL2 were mainly substitutions in pan-cancer, and the overall frequency of XCL2 mutations in pan-cancer was low, only approximately 2% in the highest UCS." (PMID 37905956, 2023). "While the overall rate of XCL2 mutation is high in human cancers, CNVs are inconsistently expressed at the mRNA level in pan-cancers (most have a negative correlation)." (PMID 37905956, 2023). "The results showed that XCL2 expression was associated with pan-cancer survival, alterations, immune infiltration, immune subtypes, and drug sensitivity." (PMID 37905956, 2023). "In human cancers, intra-tumoral CCL5, XCL1, and XCL2 transcripts closely correlate with NK cells/cDC1 gene signatures and are associated with increased overall patient survival in several cancer types." (PMID 32218226, 2020). "However, the roles of DNA methylation and XCL2 mutations in cancer development and progression require further investigation." (PMID 37905956, 2023). "However, due to a lack of clinical studies with many samples, the molecular mechanism underlying the role of checkpoint XCL2 in cancer development and targeted therapy still needs to be thoroughly investigated." (PMID 37905956, 2023). "Therefore, we explored the correlation between XCL2 methylation and mRNA expression and found that XCL2 expression was negatively associated with methylation levels in some cancers." (PMID 37905956, 2023). "Previous survival studies have found that XCL2 may be associated with the prognosis of 15 cancers." (PMID 37905956, 2023). "In this study, we found that alterations in XCL2 in cancer cells affect the prognosis of cancer patients, and that said effects may be caused by epigenetic modifications such as DNA methylation and phosphorylation that occur in cancer cells." (PMID 37905956, 2023). "In this study, we explored the expression levels of XCL2 mRNA in human organs and tissues and compared them with those observed in various cancers." (PMID 37905956, 2023). "A strong positive correlation was found between 47 known immune checkpoint genes and XCL2 expression in 33 cancers." (PMID 37905956, 2023). "The present study found that XCL2 expression was positively associated with CD8 + T lymphocytes and M1 macrophages in almost all cancers." (PMID 37905956, 2023). "In this study, we propose that XCL2 is an important chemokine whose high expression affects cancer cells by recruiting M1-type macrophages, followed by an effect that improves the prognosis of cancer patients." (PMID 37905956, 2023). "We then calculated the correlation between the expression of CD8 + T cells, macrophages, and XCL2 in 33 cancers." (PMID 37905956, 2023). "In vitro experiments were conducted to investigate the chemotactic effects of XCL2 expression on M1-type macrophages in human specimens and in isolated cancer cells." (PMID 37905956, 2023). "Using multiple immunofluorescence staining, we found that the expression level of XCL2 was upregulated in many cells in pan-cancer samples, and the number of M1 macrophage marker CD68 and INOS-positive cells increased." (PMID 37905956, 2023). "A few missense mutation sites in XCL2 were detected using the cBioPortal database, indicating a conserved pan-cancer sequence of XCL2." (PMID 37905956, 2023). "In conclusion, our findings suggest that XCL2 is a potential target for cancer immunotherapy." (PMID 37905956, 2023). "Additionally, we found that in many cancers, with an increase in pathological stage, XCL2 expression decreased." (PMID 37905956, 2023). "XCL2 expression levels increase as the disease progresses in various cancers." (PMID 37905956, 2023). "For example, XCL2 is widely distributed in cancer and various immune cells." (PMID 37905956, 2023).